ZEB1 (zinc finger E-box binding homeobox 1)
Diseases named in the same sentence as ZEB1 in open-access papers (continued):
Sharing a sentence is not in itself a finding about the gene and the disease.
breast carcinoma (continued). "Thus, these two tumor hybrids together with parental HS578T-Hyg breast cancer cells were chosen to explore the role of ZEB1 and its CRISPR/Cas9 KO in migration, invasion and prospective CSC properties." (PMID 38139138, 2023). "Interestingly, in our study, MIR497HG can be regulated by both ERα transactivation and ZEB1 epigenetic inhibition, which perform dynamic roles in endocrine sensitivity of breast cancer." (PMID 36815359, 2023). "Further research should explore the molecular mechanisms behind differences in phenotypic outcomes between the Snailhi and Snaillo models, and whether the recruitment of other transcription factors, like Zeb1 in breast cancer, are involved." (PMID 36788501, 2023). "The feedback pathway of ZEB1/miR-200a promotes the invasion and metastasis of breast cancer cells." (PMID 37904877, 2023). "Moreover, recent analyses of ZEB1 genomic binding sites in breast cancer show that ZEB1 binding sites extensively overlap with both AP-1 (33% ZEB1 overlap with c-JUN) and YAP binding sites." (PMID 37176013, 2023). "Recently, both Keymeulen’s and Yang’s groups have reported that abnormal Akt activation can induce breast cancers to switch from luminal tumors to basal-like/triple-negative breast cancers and can promote tumor metastasis via zinc finger E-box-binding homeobox 1 (ZEB1)-mediated EMT." (PMID 36400965, 2023). "Accordingly, we hypothesize that certain components of Zeb1 interactome specific for BCSCs may serve as novel therapeutic targets for treatment of breast cancer metastasis." (PMID 37372954, 2023). "Indeed, the HS578T-Hyg ZEB1-KO cells revealed a markedly higher ZEB2 expression than the HS578T-Hyg breast cancer cells." (PMID 38139138, 2023). "The ZEB1 mRNA was depleted in BCX-010CL breast cancer cells by shRNA knockdown." (PMID 37567892, 2023). "ZEB1 regulates invasion and migration of breast cancer and OC cells." (PMID 36982788, 2023). "A significant number of Zeb1 interactors belongs to the group of RNA-binding proteins that have emerged recently as important post-transcriptional modulators of carcinogenesis, but only a few have had their roles in breast cancer confirmed." (PMID 37372954, 2023). "Small molecule inhibitors undergoing clinical trials includes Curcumin (phase III, targeting NF-kB in brain tumor), Metformin (phase III, targeting ZEB1, Slug, Twist in breast cancer), Omo-103 (phase I), and Disulfiram (phase II, targeting ERK/NF-kB/Snail pathway in germ cell tumors)." (PMID 37444447, 2023). "Considering that hypoxia plays a pivotal role in ectopic Zeb1 expression in breast cancer, we determined whether Zeb1 regulates aerobic glycolysis under hypoxia." (PMID 35246504, 2022). "Moreover, a mechanism that activates ZEB1 is the asymmetric dimethylation of H4R3 by PRMT1 at the ZEB1 promoter, which promotes migration, invasion, and the acquisition of stem cell properties of breast cancer cells." (PMID 35885916, 2022). "In conclusion, these findings identify a Zeb1-dependent mechanism as a driver of breast cancer progression that acts by stimulating tumor–macrophage interplay, which could be a viable therapeutic target for the treatment of advanced human cancers." (PMID 35246504, 2022). "Since Zeb1 regulates expression of the glycolytic rate-determining enzymes HK2, PFKP and PKM2 that modulate cancer cell proliferation and/or apoptosis, the function of Zeb1 in aerobic glycolysis at least partly explains the phenotypes induced by Zeb1 depletion in breast cancer cells." (PMID 35246504, 2022). "Besides, HDAC6 can also activate the phosphorylation of signal transducer and activator of transcription 3 on Tyr-705 and upregulate ZEB1 in MDA-MB-231 breast cancer cells to enhance EMT." (PMID 36457493, 2022). "LINC00894 was reported to promote breast cancer metastasis by regulating ZEB1." (PMID 36104748, 2022).
breast carcinoma (continued). "LINC00894 enhances cell proliferation and invasion by binding with miR-429 to mediate ZEB1 expression in breast cancer (Meng, Shao & Feng, 2021); what’s more, in thyroid cancer, its increased expression reduces the oncogenic properties by sponging let-7e−5p to promote TIA-1 expression." (PMID 36570012, 2022). "Studies in breast cancer have found that Ovol2 inhibits EMT by direct transcriptional inhibition of ZEB1 expression, and studies in liver cancer have shown that Ovol2 inhibits EMT by indirectly promoting miR-200 expression, and that targeting TRPV1 can inhibit EMT by affecting the Ovol2-zeb1 axis." (PMID 35346238, 2022). "We determined with the GOBO tool whether the outcome in breast cancer patients treated with the ERα antagonist tamoxifen correlates with ZEB1 expression levels." (PMID 35440541, 2022). "We, therefore, speculate that ANXA2, HSPB1, and TIMP1, may be among the genes induced by ZEB1 during early/partial EMT stages that may change the tissue tropism of ERα+ breast cancer cells." (PMID 35440541, 2022). "Next, to determine whether glycolysis plays a role in Zeb1-mediated regulation of tumor growth in vivo, we constructed a breast cancer xenograft model using female BALB/c nude mice by treatment with OXM and/or EPI." (PMID 35246504, 2022). "Subsequently, we found that ZEB1 was highly expressed in various breast cancer cell lines." (PMID 36273188, 2022). "Meanwhile, Sahay et.al reported that ZEB1 promoted miR-21 expression in basal breast cancer." (PMID 36522730, 2022). "As a transcriptional repressor, SLFN5 prevents epithelial-mesenchymal transition (EMT) in breast cancer and targets the ZEB1 promoter to abrogate ZEB1 transcription and the downstream PTEN/AKT/cyclin D1 signaling cascade, ultimately prompting cancer cell death." (PMID 35768579, 2022). "Moreover, increased ZEB1 expression in triple-negative breast cancer patients, the breast cancer molecular subtype with worse prognosis and with an enrichment in the CSC population, is predictive of radiotherapy relapse." (PMID 35326385, 2022). "While there is still much to learn about these cells, our new findings suggest they may represent MaSCs in the activated state and display traits similar to ZEB1+ breast cancer cells." (PMID 35027548, 2022). "We thus investigated whether Zeb1-induced aerobic glycolysis affects breast cancer growth and metastasis." (PMID 35246504, 2022). "We used the luminal breast cancer cell line MCF7 and its variant MCF7-V, which displays more robust ERα responses, and the luminal breast cancer cell line T-47D to establish cells stably expressing ZEB1 from a doxycycline (DOX)-inducible (Tet-on) lentiviral vector." (PMID 35440541, 2022). "Based on these findings and our ex vivo and xenograft results, we suggest that the functional interaction between ZEB1 and ERα may alter the tissue tropism of metastatic breast cancer cells towards bone." (PMID 35440541, 2022). "Whether ZEB1 can promote breast cancer progression by activating its target gene transcription deserves to be explored." (PMID 36273188, 2022). "We wondered whether CD151 might be a therapeutic target during hybrid EMT stages when ZEB1 and ERα are simultaneously expressed in breast cancer cells." (PMID 35440541, 2022). "While the exact identity and function of these cells is still a mystery, it suggests they may be similar to ZEB1+ breast cancer cells." (PMID 35027548, 2022). "In addition, it has been reported that ZEB1 is increased in stromal cells of human breast cancers and ZEB1 deletion suppresses mammary tumour formation in a mouse model of breast cancer." (PMID 36413374, 2022). "Moreover, the P38-mediated phosphorylation of Ser367 of FOXC2 serves as a regulatory mechanism of ZEB1 in metastatic breast cancer cells." (PMID 35409206, 2022). "In breast cancer, ZEB1 expression also correlates with EMT 32,33." (PMID 35342335, 2022).
breast carcinoma (continued). "Thus, low expression of miR-200b/c induces increased expression of ZEB1/2 and vimentin, which is effective in increasing metastasis and invasion of breast cancer cells, and on the other hand, inhibits the function of Tamoxifen." (PMID 35928368, 2022). "Importantly, our study introduced the potential therapeutic approaches that disrupt the link between Zeb1-induced aerobic glycolysis and carcinogenesis, eventually leading to improvement of the clinical outcomes of patients with aggressive breast cancer." (PMID 35246504, 2022). "Moreover, OXM strongly attenuated the ability of Zeb1 to promote tumor growth in Zeb1/231 xenografts, suggesting that glycolysis induced by Zeb1 is critical for breast cancer cell growth." (PMID 35246504, 2022). "We previously showed that nPKC-θ is also a key regulator of nuclear ZEB1 in breast cancer cells." (PMID 35326747, 2022). "The unexpected role of hypoxia-induced Zeb1 expression established by our study might offer additional approaches for targeting immunosuppressive TAMs in breast cancer." (PMID 35246504, 2022). "Besides, circKIF4A promoted metastasis and reduced cell apoptosis by miR-152/ ZEB1 axis in breast cancer." (PMID 36098705, 2022). "Moreover, ZEB1 also plays an important role in EMT regulation in breast cancer cells, dramatically increasing the metastatic rate, plasticity, and therapy resistance of breast cancer." (PMID 36010901, 2022). "In breast cancer, ZEB1 is regulated by the E3 ubiquitin ligase SIAH, which marks its degradation." (PMID 36076302, 2022). "Additionally, the results from breast cancer indicate that the EMT regulators ZEB1/2 and Bmi1 promote stemness toward tumorigenesis and metastasis via TET‐Family‐dependent epigenetic modulation." (PMID 35601657, 2022). "ZEB1 induced the accumulation of MDSCs by upregulating the inflammatory cytokines in breast cancer." (PMID 36591279, 2022). "First, there may exist other molecules in micro ribonucleic acid-448 that regulates zinc finger e-box binding homeobox 1 to inhibit the growth of breast cancer cells and increase their sensitivity to chemotherapy which may have the same effects." (PMID 35905576, 2022). "To further strengthen the pathological correlation between Zeb1 expression and aerobic glycolysis in human breast cancer, we performed immunohistochemical staining for Zeb1, LDHA and MCT4 (a lactate transporter marker) in 128 samples of primary breast carcinoma." (PMID 35246504, 2022). "Moreover, we and others recently demonstrate that ZEB1 protein can promote the resistance of breast cancer to radiotherapy and chemotherapy." (PMID 34462429, 2021). "Damiano and his colleagues found that the downregulation of miR-200 in breast cancer could account for EMT and stem-like features of breast cancer by targeting ZEB1." (PMID 33722196, 2021). "So far, it remains unclear how ELF3 inhibits ZEB1 promoter activation by ETS1 in breast cancer cells." (PMID 33712555, 2021). "It will be interesting to see whether miR-203 can also attenuate the expression of Zeb2 and potentially Zeb1 in metastatic breast cancer cell models." (PMID 33414456, 2021). "PRMT1 has been demonstrated to promote the EMT program of breast cancer cells by activating ZEB1 and to confer resistance to cetuximab in TNBC cell lines, and its overexpression was correlated with cancer malignancy and poor prognosis by methylating and inactivating C/EBPα." (PMID 34360879, 2021). "MDA-MB-231 cells are categorized into the basal-like subtype of breast cancer with high levels of ZEB1/2 expression and low levels of E-cadherin expression, whereas MCF7 cells are categorized into the luminal subtype with low levels of ZEB1/2 expression and high levels of E-cadherin expression." (PMID 33712555, 2021).
breast carcinoma (continued). "We aimed to study the impact of EMT-related markers on a breast cancer cohort and specifically analyze the involvement of Snail, Twist, ZEB1, N-cadherin, Vimentin, GRHL2, E-cadherin, and EpCAM and their respective outcome on both immune infiltration of the TME and clinicopathological features." (PMID 34680248, 2021). "This process was reported to be linked to the zinc finger E-box binding homeobox 1 (ZEB1), a transcription factor inducer of the epithelial-to-mesenchymal transition (EMT), known to modulate breast cancer cell plasticity by conferring stemness properties to the cells." (PMID 33920223, 2021). "Mechanistically, we found B3GALT5 could regulate cell proliferation, migration, and invasion through EMT activator ZEB1 in breast cancer cells as well as other properties of BCSCs, such as mammosphere formation, tumor initiation, and metastasis." (PMID 33413566, 2021). "In particular, in the claudin-low subtype of aggressive breast cancer, the ZEB1/YAP/TEAD complex is shown to regulate the expression of canonical YAP/AP-1 targets and to activate genes programs linked to cell migration, cytoskeletal reorganization, and focal adhesion." (PMID 34439395, 2021). "Furthermore, factors and pathways such as ZEB1, ZEB2, Sox2, Sox9, Wnt pathway, hedgehog pathway, hippo pathway, and notch pathway are associated with CSC properties in breast cancers." (PMID 34439392, 2021). "c-Myb expression was found to correlate with levels of miR-200a, miR-200b, miR-200c and miR-141 in breast cancer samples, and transfection experiments showed that the repressive effects of ZEB1 on miR-200 expression dominate over the activating effects of c-Myb." (PMID 34884985, 2021). "Indeed, we showed that macrophage-mediated phagocytosis was activated by either blocking the EMT-dependent CD47 overexpression via anti-CD47 antibody or silencing of SNAI1 or ZEB1 via siRNA in mesenchymal MDA-MB-231 breast cancer cells." (PMID 33803139, 2021). "Specifically, Phosphoglucose isomerase (PGI), which transformed glucose-6-phosphate into fructose- 6-phosphate in the second step of glycolysis, could promote EMT by frustrating miR-200 and increasing ZEB1/2 in breast cancer cells." (PMID 35004693, 2021). "Whereas ZEB1 has been shown to confer different types of cancer drug resistance including in breast cancer, the function of CHFR in chemoresistance of TNBC cells remains unclear." (PMID 34462429, 2021). "ZEB1 is implicated as a prime element of a network of transcription factors that control cell proliferation, EMT, and cancer metastasis in various cancers including breast cancer, pancreatic cancer, and lung cancer." (PMID 33413566, 2021). "GPI promotes the EMT process of breast cancer cells by inhibiting miR-200 and inducing ZEB1/2." (PMID 35222014, 2021). "Finally, we also characterized the mechanism by which DNAJB9 regulates breast cancer cell invasion and metastasis by regulating ZEB1 and the EMT process." (PMID 33966034, 2021). "However, evidence of ZEB1 upregulation has been reported in different cancer types such as pancreatic, lung, liver, colon, and breast cancers." (PMID 34868979, 2021). "The results are in agreement with a recent report showing that ZEB1-driven EMT program may contribute to early nodal metastasis in breast cancer patients." (PMID 33413566, 2021). "Furthermore, Slfn12 regulates ZEB1 and Slug protein conversely to the mRNA in breast cancer cells and c-Myc in lung adenocarcinoma cells." (PMID 34710177, 2021). "Furthermore, depletion of the EMT-TF Zeb1 in a pancreatic cancer model or Twist in a mouse model of breast cancer almost completely diminished metastatic capacity." (PMID 34072345, 2021). "Yao and Yao found that ABCB5 may enhance the metastasis and epithelial–mesenchymal transition (EMT) in breast cancer through the downstream effector Zinc finger E-box-binding homeobox 1 (ZEB1)." (PMID 33801148, 2021).
breast carcinoma (continued). "We also found a concordant abundance of Snail and Zeb1 transcripts in BRCA (breast cancer), LUAD (lung adenocarcinoma), LUSC (lung squamous cell carcinoma) and HNSC (head and neck squamous cell carcinoma) samples, suggesting crosstalk between the Snail and Zeb1 transcripts in human cancer." (PMID 34502497, 2021). "Additionally, upregulation of PD-L1 was shown to be dependent on Zeb1 expression in breast cancer and NSCLC." (PMID 34072345, 2021). "In breast cancer cells, ZEB1 promotes radioprotection by driving the expression of the apical DDR kinase ATM via complex formation with p300 and PCAF at the ATM promoter as well as by stabilizing the mediator kinase CHK1 via sequestration of its deubiquitinase USP7." (PMID 34459003, 2021). "Collectively, these data suggest that downregulation of CHFR may contribute to overexpression of ZEB1 in human malignant breast tumors, which may lead to chemoresistance and eventually metastatic relapse." (PMID 34462429, 2021). "We used Western blotting to screen an in-house library of natural compounds to identify those that could potentially alter ZEB1 protein stability through their influence on ZEB1 expression in MDA-MB-231 breast cancer cells." (PMID 32296027, 2020). "The transcription factor Zeb1 is known to promote tumorigenesis and stemness in breast cancer." (PMID 33046710, 2020). "We analyzed impact of CTGF on other secretome analysis detected targets and could detect that reducing CTGF expression represses TGFBI, LOX and ZEB1 expression in mesenchymal transformed breast cancer cells." (PMID 33087801, 2020). "In addition, in both prostate and breast cancers, miR-205 revealed to be capable to enhance radiation response by targeting ZEB1, a well-established EMT inhibitor." (PMID 32069895, 2020). "We also performed these experiments in a coculture system of SUM-159 with HUVEC-mCherry and obtained similar results, confirming that endothelial Jag1-induced juxtacrine activation of the Notch1 receptor leads to increased Zeb1 expression in breast cancer cells." (PMID 33046710, 2020). "In addition to normal mammary epithelia, the epithelial polarity of breast cancer cells can be partially restored by knockdown of ZEB1 to accumulate LLGL2 in the cytoplasm." (PMID 32014049, 2020). "Therefore, Zeb1 depletion in breast cancer cells impairs VEGFA paracrine signaling in adjacent endothelial cells to subvert a Jag1-mediated perivascular niche." (PMID 33046710, 2020). "On the other hand, ZEB1 contributes to the formation of the tumor microenvironment by regulating the levels of various inflammatory cytokines, such as interleukin 6/8 (IL-6/8), which resulted in increased tumor growth in basal-like breast cancer cells." (PMID 32014049, 2020). "However, the exact regulatory mechanisms of ZEB1 in breast cancer cell proliferation and invasion remain to be elucidated." (PMID 32850368, 2020). "In clinical studies, ZEB1 was found to be significantly associated with the depth of invasion, lymph node metastasis and TNM stage in digestive cancer patients, as well as in patients with breast cancer." (PMID 32014049, 2020). "ZEB1 can induce EMT in breast cancer cells via activation of PD-L1." (PMID 32664703, 2020). "The Hippo signalling pathway effector YAP has been shown to drive ZEB1 expression in breast cancer." (PMID 32796736, 2020). "Knockdown of Snail but not Slug induced mesenchymal-to-epithelial transition, leading to loss of Zeb1 and reactivation of E-Cadherin in MDA-MB-231 breast cancer cells, which was further associated with an attenuated primary tumor growth and a strongly suppressed metastatic spreading." (PMID 32430004, 2020). "However, we found that when SIX‐1 was overexpressed in breast cancer cells, the multiple of ZEB1 mRNA increase was significantly lower than that of ZEB1 protein increase." (PMID 32227618, 2020). "Moreover, ZEB1 protein expression has some predictive outcome during neoadjuvant therapy in breast cancer patients." (PMID 32158360, 2020).